ULK3 (unc-51 like kinase 3)
Description:
Serine/threonine protein kinase that acts as a regulator of smoothened signaling and autophagy. Acts as a positive regulator of smoothened signaling in the presence of hedgehog (DHH, IHH or SHH) ligand: autophosphorylates and mediates phosphorylation of full-length GLI2, promoting subsequent phosphorylation by CDK1 and GLI2 dissociation from SUFU and translocation to the nucleus. Also phosphorylates as GLI1 and GLI3, although less efficiently. In the absence of hedgehog ligand, interacts with SUFU, thereby inactivating the protein kinase activity and preventing phosphorylation of GLI proteins (GLI1, GLI2 and/or GLI3). Also acts as a regulator of autophagy: following cellular senescence, able to induce autophagy.
Synonyms: DKFZP434C131; FLJ90566
Tractability: Small molecule: a structure with a bound ligand is known; a high-quality ligand is known; it belongs to a druggable protein family. PROTAC: it is named in the literature on targeted protein degradation; ubiquitination databases record sites on it; a small molecule that binds it is known.
Target class: Kinase; Other protein kinase group; Other protein kinase ULK family; Enzyme; Protein Kinase
Gene: Protein-coding gene on chromosome 15 (74,836,116 to 74,843,346, reverse strand). Ensembl gene ENSG00000140474.
Subcellular location: Cytoplasm
Subcellular location (Human Protein Atlas): Acrosome
Pathways (Reactome):
Signal Transduction: Hedgehog 'on' state
Gene Ontology:
Molecular function: protein binding; protein serine/threonine kinase activity; ATP binding; protein kinase activity; protein serine kinase activity
Biological process: fibroblast activation; positive regulation of smoothened signaling pathway; protein autophosphorylation; smoothened signaling pathway; autophagosome assembly; autophagy; cellular senescence; mitophagy; piecemeal microautophagy of the nucleus; regulation of autophagy; response to starvation; reticulophagy
Cellular component: cytoplasm; ciliary tip; cytosol; phagophore assembly site; phagophore assembly site membrane
Genetic constraint (gnomAD): Loss-of-function variants: 54 observed, 58.35 expected, observed/expected ratio (o/e) 0.93, 90% interval 0.74 to 1.16. The upper end of that interval is the gene's LOEUF score, 1.16, which puts it in group 5 of 6, group 1 being the genes least tolerant of losing a copy. Missense variants: 556 observed, 535.08 expected, observed/expected ratio (o/e) 1.04, 90% interval 0.97 to 1.12. Synonymous variants: 239 observed, 212.69 expected, observed/expected ratio (o/e) 1.12, 90% interval 1.01 to 1.25.
Homologues: Orthologues: pig ULK3 (97% identical), rat Ulk3 (95% identical), mouse Ulk3 (94% identical), chimpanzee ULK3 (93% identical), macaque ULK3 (93% identical), guinea pig ULK3 (93% identical), dog ULK3 (80% identical), tropical clawed frog ulk3 (72% identical), rabbit ULK3 (67% identical), zebrafish ulk3 (48% identical), Drosophila melanogaster Aduk (42% identical). Paralogues in human: ULK1 (35% identical), ULK2 (33% identical).